APP (amyloid beta precursor protein)
Diseases named in the same sentence as APP in open-access papers (continued):
Sharing a sentence is not in itself a finding about the gene and the disease.
Alzheimer disease (continued). "To prove the suitability and sensitivity of NAD(P)H FLIM in analyzing mitochondrial function in a pathological context, we applied it on an APP-overexpressing model of Alzheimer’s disease (AD)." (PMID 29181426, 2017). "Recently, we and others have shown that GULP1 PTB domain binds to Alzheimer’s disease amyloid precursor protein (APP)." (PMID 29245900, 2017). "The mouse model of Alzheimer’s disease (AD), Tg2576 mice (APP), has provided valuable information, such as the role of the metallothionein (MT) family in their behavioral and amyloidosis phenotypes." (PMID 28134760, 2017). "Overexpression of Nrf2 specifically in hippocampal neurons alleviates cognitive dysfunction in APP/PS1 mice suggesting that Nrf2 activation in neurons is sufficient to prevent neuronal dysfunction in Alzheimer’s disease." (PMID 28820437, 2017). "Amyloid Beta Precursor Protein Is involved in promoting transcriptional activation; can participate in the formation of amyloid plaques of Alzheimer disease." (PMID 28993790, 2017). "Amyloid precursor protein (APP) is cleaved by β-site amyloid precursor protein-cleaving enzyme 1 (BACE1) to produce β-amyloid (Aβ), a critical pathogenic peptide in Alzheimer’s disease (AD)." (PMID 28109317, 2017). "The role of exosomes in Alzheimer's disease was further explored and a novel secretion pathway of APP metabolites, including C-terminal fragments (CTFs) of APP, mediated by exosome vesicles, has been demonstrated." (PMID 28912682, 2017). "Caspase-6-mediated cleavage of mutant huntingtin protein and amyloid precursor protein (APP) is critical for the onset of Huntington’s disease and Alzheimer’s disease respectively." (PMID 28659495, 2017). "In an Alzheimer’s disease (AD) model, the APP/PS1 transgenic mice, RS occurs at a young age and before the onset of the disease." (PMID 28981461, 2017). "Aberrant APP signaling epistatically activates FOXO1 inducing cell death in Alzheimer’s disease (AD) mouse models." (PMID 29066835, 2017). "The peptide modulated 77 genes, of which 65 are listed in the AlzBase database and include the hallmarks of Alzheimer’s disease: APP, APOE, PSEN1, and PSEN2." (PMID 28798312, 2017). "While many studies have been focused on the pathologic role of APP in Alzheimer's disease, the physiological functions of APLP1 have remained largely elusive." (PMID 28537903, 2017). "By now, there is good evidence from multiple lines of research that specific domains of APP do indeed contribute to amyloid plaques as found in patients with Alzheimer’s disease (AD; Hardy and Selkoe, 2002)." (PMID 28210211, 2017). "Disturbed amyloid precursor protein (APP) processing is considered to be central to the pathogenesis of Alzheimer’s disease (AD)." (PMID 28209190, 2017). "Resveratrol 20 was demonstrated to induce autophagy by inducing Adenin mononucleotide phosphate kinase (AMPK) signaling in a double transgenic Amyloid precursor protein (APP)/Presenillin1 (PS1) mouse model with Alzheimer’s disease." (PMID 28106854, 2017). "Of relevance herein, two overexpressed proteins are APP and amyloid-beta, which have been well-studied in Alzheimer's disease (AD)." (PMID 28223919, 2017). "Here, the authors use non-destructive microscopy approaches to study the confirmation of Aβ and APP in mouse models of Alzheimer's disease." (PMID 28287086, 2017). "In another work concerning ATF4, APP/PS1 mice (double transgenic mice expressing a chimeric mouse/human amyloid precursor protein and a mutant human presenilin 1 in their neurons), an established animal model of Alzheimer’s disease, was used." (PMID 29065505, 2017). "The amyloid precursor protein (APP) was first described as the source of amyloidogenic peptides that play a central role in the pathophysiology of Alzheimer’s disease." (PMID 28878618, 2017). "Taken together, our study explored the benefits of BJJS treatment on APP/PS1 mice during the pathological process of Alzheimer's disease from a macro and micro perspective." (PMID 29190943, 2017).
Alzheimer disease (continued). "In this study, we investigated the distribution of intravenously transplanted syngeneic MSCs derived from young and aged mice into young, aged, and transgenic APP/PS1 Alzheimer’s disease mice." (PMID 28420415, 2017). "Genetic and biochemical evidence establishes a central role of amyloid precursor protein (APP) in Alzheimer’s disease (AD)." (PMID 28785723, 2017). "In Alzheimer’s disease (AD), dysregulation of APP leads to excess Aß and neuronal dysfunction; suggesting that neuronal APP/Aß trafficking can be targeted for therapeutic gain." (PMID 27966067, 2017). "The total probability value for Alzheimer's disease presence due to alterations in Ab, Tau/TotalTau, age/inheritance, APP, APOE4 and Vascular disorders of the patient." (PMID 28408880, 2017). "The APP protein products are known to be involved in the pathogenesis of Alzheimer disease, and seem to have an important role in copper homeostasis as well." (PMID 28459846, 2017). "The “amyloid cascade hypothesis” of Alzheimer's disease (AD) proposes disease is caused by accumulation of the β-amyloid (Aβ) peptide (typically up to 42 residues in length) that is proteolytically derived from the amyloid precursor protein (APP; Hardy and Higgins, 1992; Masters and Selkoe, 2012)." (PMID 28626387, 2017). "The anti-amyloid β mAb was found to normalize synaptic function and improve cognitive function in amyloid precursor protein (APP) transgenic mouse model of Alzheimer's Disease." (PMID 28475417, 2017). "Such a redundancy is not uncommon in developmental processes and pathogenesis of diseases, e.g., matrix metalloproteinases (MMPs) in embryonic development and amyloid precursor protein (APP) genes in Alzheimer‘s disease." (PMID 28559854, 2017). "Alzheimer’s disease (AD) is the most common neurodegenerative disease, and is characterized by the abnormal processing of the amyloid precursor protein (APP) through the amyloidogenic pathway, and the hyperphosphorylation of TAU protein." (PMID 28800101, 2017). "Next, we also confirmed the significantly higher expression of the AD litmus gene (Spc25) in mouse neuronal T4 cells treated with mouse sera from 16-month-old APP transgenic mice, an Alzheimer’s disease model (APPswe/PS1dE9)." (PMID 29203810, 2017). "Here we report that bexarotene improves neuron survival and reduces intraneuronal APP/Aβ deposition in an aggressive mouse model of Alzheimer’s disease." (PMID 28205585, 2017). "Excessive generation of amyloid-β peptide (Aβ) by aberrant proteolysis of amyloid precursor protein (APP) is a key event in Alzheimer's disease (AD) pathogenesis." (PMID 28963516, 2017). "Mutations in the amyloid protein precursor (APP), presenilin-1 (PSEN1), and presenilin-2 (PSEN2) genes are a known cause of familial, early-onset Alzheimer disease (EOAD) (onset below age 65)." (PMID 28350801, 2017). "Discovered during the 1980s as precursor protein of A-beta (Aβ)—the main constituent of senile plaques—much effort has been made to understand the pathophysiology of Alzheimer’s disease (AD) and the physiological function of APP." (PMID 28265241, 2017). "The O-GlcNAc modification of amyloid precursor protein (APP) carries special importance; inadequate proteolysis of APP produces amyloid-beta, which is a hydrophobic peptide and the major hallmark of Alzheimer's disease (AD)." (PMID 29456783, 2017). "Previously, our group showed that 5LO influences the Alzheimer’s disease (AD) phenotype of APP transgenic mice as well as a mouse model with plaques and tangles." (PMID 29249809, 2017). "Following the discovery that the amyloid precursor protein (APP) is the source of β-amyloid peptides (Aβ) that accumulate in Alzheimer’s disease (AD), structural analyses suggested that the holoprotein resembles a transmembrane receptor." (PMID 28197070, 2017). "Previous studies have shown that exercise can prevent white matter atrophy in APP/PS1 transgenic Alzheimer’s disease (AD) mice." (PMID 29029478, 2017).
Alzheimer disease (continued). "Extracellular accumulation of Aβ generates amyloid plaques in Alzheimer’s disease (AD), whereas alternative cleavage of APP by α-secretase produces neuroprotective fragments." (PMID 29118375, 2017). "Amyloid precursor protein (APP) processing and the accumulation of APP-derived amyloid β (Aβ) peptides are key processes in Alzheimer's disease (AD)." (PMID 28285880, 2017). "Although APP processing and β-amyloid production play a central role in Alzheimer’s disease (AD) pathogenesis, the physiological function of APP remains elusive." (PMID 28785723, 2017). "It was reported that i-proteasome was up-regulated in senile hippocampus which involves in the clearance of accumulated amyloid precursor protein (APP) in Alzheimer's disease (AD)." (PMID 27570618, 2016). "In a mouse model of Alzheimer's disease, bringing two mutations on APP (amyloid precursor protein) and presenilin 1, chronic progesterone treatment for 3–6 months improved object recognition performance." (PMID 28090360, 2016). "The modified procedures were applied to paraffin sections of a mouse model (APP/PS1) of Alzheimer’s disease." (PMID 27683879, 2016). "TDP-43 shares similar features with the Aβ precursor protein (APP) in Alzheimer’s disease, as both proteins are cleaved before aggregation." (PMID 26883171, 2016). "γ-secretase is responsible for the proteolysis of amyloid precursor protein (APP) into short, aggregation-prone amyloid-beta (Aβ) peptides, which are centrally implicated in the pathogenesis of Alzheimer’s disease (AD)." (PMID 27580372, 2016). "To date, more than 35,000 research articles dealing with the amyloid precursor protein (APP) are annotated in Pubmed (13.10.2016) and most of these papers are related to Alzheimer's disease." (PMID 28105004, 2016). "Our work has shown that the central molecule in Alzheimer's disease, APP, binds to and activates the PIKfyve complex." (PMID 26934981, 2016). "We tested seizures in two alternative Alzheimer's disease mouse models, R1.40 and J20, which exhibit elevated APP expression." (PMID 28018172, 2016). "In a brain of Alzheimer disease patients one can find an accumulation of beta-amyloid protein plaques which are formed from a peptide excised from APP protein by β (BACE1) and γ-secretases (PSEN1)." (PMID 26851889, 2016). "Our recent work has shown that the intracellular domain of the amyloid precursor protein (APP), a molecule central to the aetiology of Alzheimer's disease binds to VAC14 and enhances PIKfyve function." (PMID 26934981, 2016). "The amyloid precursor protein (APP) is well known to be involved in the pathophysiology of Alzheimer's disease (AD) via its cleavage product amyloid ß (Aß)." (PMID 28163673, 2016). "Amyloid precursor protein (APP) and its cleavage product amyloid β (Aβ) have been thoroughly studied in Alzheimer’s disease." (PMID 27383650, 2016). "APP is a molecule known to be of central importance in Alzheimer’s disease, a progressive, neurodegenerative disease that results in debilitating incapacity of patients and is ultimately fatal." (PMID 26216398, 2016). "Mint/X11 is one of the four neuronal trafficking adaptors that interact with amyloid precursor protein (APP) and are linked with its cleavage to generate β‐amyloid peptide, a key player in the pathology of Alzheimer's disease." (PMID 26865271, 2016). "The proteolytic products of APP which are secreted into extracellular space play an important role in the pathogenesis of Alzheimer's disease." (PMID 26881108, 2016). "Increasing evidence suggest that molecular players in Alzheimer disease, including amyloid precursor protein (APP) and presenilin 1 (PS1) and its metabolites, play a role in adult neurogenesis." (PMID 27303258, 2016). "Amyloidogenic pathway in Alzheimer's disease (AD) involves breakdown of APP by β-secretase followed by γ-secretase and results in formation of amyloid beta plaque." (PMID 27190510, 2016).
Alzheimer disease (continued). "Consistent with this idea, we found that CYFIP2 protein expression is reduced in an APP transgenic mouse line, the Tg2576 mouse, which models early Alzheimer’s disease (Hsiaoet al., 1996;Stewartet al., 2011)." (PMID 27524794, 2016). "Conclusive genetic as well as biochemical evidence has demonstrated that APP cleavage by beta- and gamma-secretase, producing beta-amyloid on the one hand and destroying APP on the other is a key event in Alzheimer’s disease." (PMID 26216398, 2016). "For instance, several proteins involved in Alzheimer’s disease, including β-amyloid precursor protein (APP) and presenilins, are known to be cleaved by caspases." (PMID 28025335, 2016). "Cross-linking of amyloid precursor protein (APP) at the cell surface by antibodies leads to APP internalization via Arf6-depedent macropinocytosis, potentially contributing to Alzheimer's disease." (PMID 27672367, 2016). "γ-secretase mediates the intramembranous proteolysis of amyloid precursor protein (APP) and determines the generation of Aβ which is associated with Alzheimer’s disease (AD)." (PMID 27835671, 2016). "We investigated the proliferative dynamics of microglial cells and the expression of the components of the CSF1R pathway in a relevant model of Alzheimer’s disease-like pathology (APPswe, PSEN1dE9; APP/PS1)." (PMID 26747862, 2016). "Amyloid precursor protein (APP) is critically involved in the pathophysiology of Alzheimer’s disease, but its physiological functions remain elusive." (PMID 26905287, 2016). "Of the three APP family members, APP is the most studied, notorious for its cleavage generating the β amyloid peptide that contributes to Alzheimer's disease." (PMID 26840089, 2016). "Mutations in APP, APOE, PSEN1, PSEN2 and MAPT genes were found to cause Alzheimer’s disease pathogenesis." (PMID 26784894, 2016). "Several studies have shown co-localization of APLP1 with APP in control subjects and Alzheimer’s disease brain plaques." (PMID 27186164, 2016). "It is currently unclear how the balance of these two APP peptides will ultimately affect the pathological and cognitive changes in Alzheimer’s disease patients." (PMID 27456313, 2016). "The highly characterized Swedish mutant Tg2576 transgenic mouse model for Alzheimer's disease contains human APP and has Aβ plaques deposits as early as 9 months old, leading to increased memory decline with age." (PMID 27478531, 2016). "Aβ peptides derive from amyloid precursor protein (APP) processing and accumulate in Alzheimer's disease, forming the amyloid plaques." (PMID 27313835, 2016). "Numerous mouse models that express altered APP or metabolite levels exhibit elevated rates of spontaneous or provoked seizures while suppression of transgenic APP in Alzheimer's disease mice during postnatal development delays the onset of EEG abnormalities." (PMID 28018172, 2016). "APP and Tau are involved in brain development, gene expression but when are impaired, they contribute to Alzheimer’s disease progression." (PMID 27875990, 2016). "A number of mutations in APP and PSEN1 genes were identified as a cause of hereditary form of Alzheimer disease." (PMID 26851889, 2016). "This interplay is likely to be perturbed by aberrant APP processing as observed in Alzheimer’s disease." (PMID 26216398, 2016). "The accumulation of amyloid plaques derived by proteolytic cleavage of APP is one of the leading hallmarks of Alzheimer’s disease (AD)." (PMID 26905287, 2016). "For example, amyloid precursor protein fragments (APP) or tau phosphorylated at Thr181 are established biomarkers for Alzheimer’s disease, and phosphorylated tau or α-synuclein are relevant for Parkinson’s disease." (PMID 27199663, 2016). "A significant body of literature has established that APP is aberrantly processed in Alzheimer's disease." (PMID 26934981, 2016). "Patients diagnosed with Alzheimer's disease are expressed with the deposition of insoluble or oxidised amyloid-β derived from APP present in the brain." (PMID 27656235, 2016).
Alzheimer disease (continued). "Of particular importance seems an increase in the content of two proteins playing a major role in the pathogenesis of Alzheimer’s disease: APP, a direct precursor of β-amyloid, and ITM2B (BRI2), which is a physiological suppressor of β-amyloid production." (PMID 27727329, 2016). "A major rate-limiting step for Aβ generation and deposition in Alzheimer’s disease brains is BACE1-mediated cleavage (β-cleavage) of the amyloid precursor protein (APP)." (PMID 27875558, 2016). "Using qPCR, we confirmed glutamate-induced upregulation, normalized by candesartan, of a number of these genes, including several factors with fundamental roles in APP metabolism and Alzheimer’s disease, such as ADAM metallopeptidase domain 17 and APOE." (PMID 26822027, 2016). "A good example for this reasoning is the discovery of the involvement of Amyloid Precursor Protein (APP) misprocessing in Alzheimer's Disease." (PMID 27200086, 2016). "ADAM10-mediated cleavage of the amyloid precursor protein (APP) prevents the formation of the amyloid peptide Aβ, a major component of amyloid plaques observed in Alzheimer’s disease." (PMID 26686862, 2016). "We also found that chromosome mis-segregation was associated with all types of Alzheimer’s disease, including sporadic and familial Alzheimer’s disease (i.e., patients carrying a mutation in either of the presenilin (PS1 or PS2) genes or in the APP gene." (PMID 29516054, 2016). "Using MRS, we monitored the brain metabolic response to lipopolysaccharides (LPS)-induced microglia activation in vivo in a transgenic mouse model of Alzheimer’s disease (APP/PS1) and healthy controls (wild-type (WT) littermates) over 4 hours." (PMID 26813748, 2016). "β-Secretase 1 (BACE1) is a key enzyme in Alzheimer’s disease pathogenesis that catalyses the amyloidogenic cleavage of amyloid precursor protein (APP)." (PMID 27138913, 2016). "Here, we studied the organization of in vitro gamma oscillations in the MEC and LEC of the transgenic (tg) amyloid precursor protein (APP)-presenilin 1 (PS1) mouse model of Alzheimer’s Disease (AD) at 4–5 months of age." (PMID 27833535, 2016). "In order to generate a better model for Alzheimer’s disease (AD), the APP21 rat line was used to generate double transgenic line that over-expressed Presenilin 1 (PS1) with L166P mutation in addition to APP transgene (APP + PS1 line)." (PMID 27388605, 2016). "The metalloprotease meprin β cleaves the Alzheimer’s Disease (AD) relevant amyloid precursor protein (APP) as a β-secretase reminiscent of BACE-1, however, predominantly generating N-terminally truncated Aβ2-x variants." (PMID 26895626, 2016). "The Amyloid precursor protein (APP) is a key factor in Alzheimer’s Disease (AD) because, as the name implies, it is the precursor from which the neurotoxic Aβ peptides are generated." (PMID 27507933, 2016). "In CePPIN, the node with the highest degree and betweenness centrality is APP protein which has been a promising research hotspot recently for its close relationship with Alzheimer disease (AD)." (PMID 27694936, 2016). "APP and its derivatives have been shown to play a central role in Alzheimer’s disease (AD), a progressive neurodegenerative disease characterized by memory decline." (PMID 28008309, 2016). "The Amyloid precursor protein (APP) has mainly been investigated in connection with its role in Alzheimer’s Disease (AD) due to its cleavage resulting in the production of the Aβ peptides that accumulate in the plaques characteristic for this disease." (PMID 27507933, 2016). "Amyloid beta/A4 precursor protein (APP) has been shown essential roles in Alzheimer’s disease (AD) and in autism." (PMID 27266699, 2016). "The deposition of Aβ plaques is believed to play an important role in the pathogenesis of Alzheimer’s disease (AD), and accordingly, a vast amount of literature exists about the pathological roles of APP and its proteolytic products." (PMID 27114849, 2016).